GSK3B (glycogen synthase kinase 3 beta)
Diseases named in the same sentence as GSK3B in open-access papers (continued):
Sharing a sentence is not in itself a finding about the gene and the disease.
tumor (continued). "GSK3β, a kinase with tumor-suppressive roles, is often inactivated in cancer." (PMID 40996961, 2025). "GSK3B facilitates tumor cell maintenance, spread, tumor invasion, and resistance to therapies." (PMID 39820173, 2025). "The interrelation between the PAM and Wnt pathways provided by GSK3β could enable the tumor cells to simultaneously activate both pathways in order to survive." (PMID 41465855, 2025). "In this study, we focused on GSK3β, a key regulator of tumor apoptosis and metastasis." (PMID 40495167, 2025). "Moreover, HMGCR upregulates PD-1 expression in Tregs via the p38 MAPK/GSK3β axis, thereby enhancing Tregs’ suppression of antitumor immunity and supporting tumor progression." (PMID 41450917, 2025). "Further studies are needed to clarify the contexts in which GSK3β acts as a tumor promoter versus a suppressor, which could inform the design of more effective cancer treatments." (PMID 41190025, 2025). "Enrichment of pathways suggests that GSK-3β may promote TNBC progression by modulating both tumor-intrinsic and microenvironmental mechanisms." (PMID 41321870, 2025). "Additionally, cells with GSK3β inhibition exhibited reduced clonogenic and migration activities, which underscore the tumor-suppressive potential of AMPK in cancer cells." (PMID 39955067, 2025). "However, GSK-3β has dual roles in various cancer types, acting as both a tumor suppressor and an oncogene." (PMID 39948552, 2025). "Numerous studies propose GSK-3β as a potential tumor suppressor." (PMID 40656954, 2025). "The mechanisms by which GSK3B might be playing tumor-promoting function remain unclear, though other studies point to GSK3B as a regulator of metabolic reprogramming in cancer." (PMID 41441397, 2025). "GSK3β has a dual role in cancer, acting as both a tumor suppressor and promoter." (PMID 41190025, 2025). "In contrast, tumor growth was dramatically increased in the GSK-3β-KM (K85M) group." (PMID 39660100, 2025). "Leveraging advanced bioinformatics techniques, the identification of 12 crucial genes (ETNK1, BICRA, IL-1R1, KDM3A, ARID2, GSK3β, EZH2, NOTCH1, SMARCA4, FOS, CREB1, CASP3) associated with the tumor-suppressing miR-101-3p network stands out as a notable achievement." (PMID 40074445, 2025). "Emodin exerts anti-tumor effects by promoting GSK-3β-mediated PD-L1 proteasomal degradation and enhancing the anti-tumor effects of CD8+ T cells, indicating that emodin may be a promising therapeutic option for HCC." (PMID 40804393, 2025). "Due to its role in these diverse processes, GSK3β may function as either a tumor suppressor or promoter, with its effect varying based on the specific context and cancer type." (PMID 41153674, 2025). "However, increasing evidence suggests that dysregulation or aberrant expression of GSK3β facilitates tumor progression." (PMID 39762409, 2025). "Tailoring GSK-3β modulation to the immune phase and cellular context may ultimately unlock its full therapeutic potential in driving effective and durable anti-tumor responses." (PMID 40649856, 2025). "GSK3β levels are consistently higher in tumor samples compared to normal tissue." (PMID 40943055, 2025). "This suggests that transient inhibition of GSK-3β during the priming phase of DC vaccination could serve as a potent strategy to boost initial anti-tumor immunity." (PMID 40649856, 2025). "Study shows that tumor matrix stiffening can activate mammalian target of rapamycin 1 (mTORC1) and achieve cell death resistance under matrix detachment through the integrin-glycogen synthase kinase 3 beta (GSK3β)-FTO-mTOR axis." (PMID 40356596, 2025). "Given the critical roles of ERK1/2 and GSK3β signalings in promoting tumor malignancy." (PMID 39744168, 2025).
tumor (continued). "In addition, some studies have found that GSK-3β is part of a tumor suppressor complex consisting of Axin and APC that phosphorylates the oncoprotein β-catenin." (PMID 40157890, 2025). "ZSD, administered orally, inhibited the growth of Lewis LC in a subcutaneous allograft model, increased necrosis and inflammatory cell proliferation in the tumor tissues, and caused LC cells to undergo apoptosis by downregulating the levels of p-AKT, p-GSK-3β, β-catenin, and Bcl-2." (PMID 41217667, 2025). "Furthermore, the overexpression of GSK-3β has been demonstrated to augment the inhibitory effects of Erastin, a compound recognized for inducing cancer cell death and thereby attenuating tumor growth." (PMID 40656954, 2025). "Increasing evidence indicates that dysregulated signaling pathways and the tumor immune microenvironment play key roles in its progression, yet the prognostic and therapeutic value of specific regulators such as GSK-3β remains unclear." (PMID 41321870, 2025). "This may facilitate the evasion of immune surveillance, indicating that GSK-3β functions in both tumor progression and immune escape." (PMID 41321870, 2025). "Furthermore, ASPH inhibits GSK3β phosphorylation, interfering with upstream kinase communication, delaying cellular senescence, and promoting tumor progression." (PMID 41312363, 2025). "The GSK-3β/β-catenin pathway has been reported to be involved in a variety of important cellular functions and is abnormally activated in a variety of malignancies, leading to tumor progression." (PMID 39901136, 2025). "The inhibition of GSK3β can lead to β-catenin stabilization, which in turn promotes autophagy and may potentially mitigate tumor progression in cancerous conditions." (PMID 41190025, 2025). "Therefore, it is reasonable to infer that GSK-3β, β-catenin, and their target gene C-myc contribute to tumor radioresistance." (PMID 40078194, 2025). "Together, these data indicate the different roles of 53BP1-null versus the 53BP1 T334A mutation on regulation of DSB repair; furthermore, overcoming PARPi resistance through pharmacological targeting of the GSK3B-53BP1 axis requires functional 53BP1 in tumor cells." (PMID 41243969, 2025). "The possible mechanism by which BI synergistically enhances the anti-tumor efficacy mediated by 5-FU was further investigated in a pathway of glycogen synthase kinase-3β (GSK-3β), which may be a target of BI to regulate the anti-tumor effects of 5-FU." (PMID 39241034, 2024). "GSK-3β is a multifunctional serine/threonine kinase that participates in a variety of signaling pathways and plays a role in promoting apoptosis in different types of cells and various organs such as nerve cells, cardiomyocytes, and tumor cells." (PMID 38596082, 2024). "Given the significant inhibitory effect of the GSK3β and P65 inhibitors on tumor growth and LNM in CCA animal studies, we hypothesized that the PDGF-BB/PDGFR-β-GSK3β/P65 axis is a potential therapeutic target in CCA." (PMID 37307823, 2024). "In vivo experiments demonstrated that GSK3B inhibition slowed xenograft tumor growth." (PMID 39166606, 2024). "GSK3B inhibitors suppressed xenograft tumor growth in several mouse models." (PMID 39166606, 2024). "In Mia PaCa‐2 cells, the suppression of GSK‐3β inhibits mutant KRas‐dependent tumor growth and the depletion of GSK‐3β increases β‐catenin levels and forces the expression of β‐catenin mutants that lack GSK3 phosphorylation sites and are thus insufficient to induce apoptosis." (PMID 39632551, 2024). "Inhibition of FAK in ALK/MYCN tumor cells increased GSK3β activity." (PMID 38451815, 2024). "Therefore, variants within the recognition site of GSK3B could affect its phosphorylation and alter the normal function of the protein; since β-catenin is involved in cell–cell adhesion and transcriptional regulation, this variant could promote tumor development." (PMID 39202333, 2024).
tumor (continued). "RT-qPCR analysis of mRNA expression in tumor tissues revealed that compared to the empty vector group, CHMP4C overexpression significantly increased the expression of CHMP4C and β-catenin in mouse tumor tissues (p < 0.0001) and significantly decreased GSK3β expression (p < 0.001)." (PMID 38720781, 2024). "We mainly address a significant and novel mechanism that the usage of PPIs could directly induce the expression of PD‐L1 by inducing GSK3β phosphorylation and facilitate primary tumor progression and metastasis." (PMID 38752436, 2024). "GSK3B inhibitors demonstrated therapeutic efficacy in various mouse xenograft tumor models." (PMID 39166606, 2024). "The nuclear localization of GSK3β could be related to intrinsic tumour features and aberrant expression of different signalling pathways as Wnt/β-catenin or loss of phosphatidylinositol 3-kinase (PI3K)-Akt signalling." (PMID 38528037, 2024). "This suggests that TBRG4 may participate in the proliferation and migration of tumor cells through the DDX56/p-AKT/GSK3β signaling pathway." (PMID 38347489, 2024). "Xenograft tumors were used to evaluate the effect of GSK3B on tumor growth." (PMID 39166606, 2024). "The increased expression of AQP3 in tumor stem cells may lead to the downregulation of genes linked to the Wnt/GSK-3β/β-catenin pathway, specifically GSK-3β and β-catenin." (PMID 39440058, 2024). "Furthermore, combined treatment with PQR309 and gemcitabine reduced p-STAT3, HSP60, p-GSK-3β protein levels in the xenograft tumor tissues, according to western blotting analysis." (PMID 38555280, 2024). "AQP3 may affect tumor progression by reducing differentiation and inhibiting apoptosis of LC stem cells through the Wnt/GSK-3β/β-catenin pathway." (PMID 39346734, 2024). "We found that the highest scoring tumor-associated signaling was the ErbB signaling pathway, and triptonodiol may act by directly targeting PKC, PAK, and GSK3B, which is consistent with the results of the PPI network." (PMID 38017514, 2023). "Our results establish MTX as a macrophage reprogramming drug and evidence that its therapeutic benefits go beyond limiting tumor cell proliferation, suggesting that GSK3β might be the final target of the antitumor strategies, aiming at CSF1R or PI3Kγ." (PMID 36380627, 2023). "The PI3K/AKT/GSK-3β pathway also plays a crucial role in regulating tumor cell apoptosis." (PMID 37899170, 2023). "This suggests an increased activity of GSK3B in tumor tissues from these patients." (PMID 36520032, 2023). "Induction of GSK3β inactivation by EGF in tumor cells leads to increased glycosylation PD-L1." (PMID 37554324, 2023). "In vivo experiments or other approaches that mimic the harsh tumor microenvironment may be able to show the effect of these metabolic improvements on anti-tumor activity of GSK3B-KO NK cells." (PMID 36765663, 2023). "In PTEN-deficient cancers, AKT activation-induced GSK3β suppression results in the disruption of CHD1 proteolysis and aberrant accumulation of the CHD1 protein, which contributes to tumor development and tumor microenvironment (TME) remodeling." (PMID 36776288, 2023). "NDRG1 pleiotropy is driven by TGFβ to differentially promote metastasis and/or maintenance of CSCs at different stages of tumor progression, which could be abrogated by the inhibition of TGFβ and GSK3β." (PMID 36594086, 2023). "We suspect this bias may be related to the source and species specificity, D2 receptor activity, and initial activation of Wnt/GSK3β/β-catenin signaling pathway in the tumor stem cells'." (PMID 37649087, 2023). "Moreover, this ubiquitination inhibits MafA transcriptional activity driven by GSK3β therefore suppressing MM cell proliferation and tumor growth." (PMID 37028761, 2023). "In addition, since overexpression of miR-4465 negatively regulates GSK-3β expression, we expected it to function as a tumor suppressor in RCC, but on the contrary, worse clinical characteristics were observed in the upregulated group." (PMID 37754254, 2023).
tumor (continued). "Additionally, high levels of GSK-3β expression were associated with reduced relapse-free survival, while GSK-3β inhibitors were shown to suppress tumor growth in BC patients." (PMID 37922300, 2023). "Mechanistically, miR-29a-3p functioned as a tumor-promoting factor by downregulating the FOXO3-AKT/GSK3β axis and subsequently suppressing the expression of PD-L1, which was a known target molecule for anti-tumor immunotherapy, to shield OC cells from immune escape." (PMID 36355327, 2023). "In addition to its role in suppressing tumor development and progression, GSK-3β is also pivotal to several pro-oncogenic pathways (e.g., Wnt/β-catenin-, Hedgehog-, Notch- and c-myc-mediated signaling)." (PMID 37108703, 2023). "Our results indicated that the combination of Plasmodium infection and Gem treatment significantly suppressed tumor metastasis and EMT, and these suppressions were potentially associated with the blockade of CXCR2/TGF-β-mediated PI3K/Akt/GSK-3β/Snail signaling pathway." (PMID 37916167, 2023). "PARPi could upregulate PDL-1 expression by inactivating Glycogen synthase kinase-3 beta, increasing tumor cell toxicity while inhibiting T-cell activation." (PMID 40778076, 2023). "Depending on the tumor type, GSK-3β can be either a tumor promoter or suppressor." (PMID 37922300, 2023). "We found that GSK3A and GSK3B are activated in GAC tumor tissues with lymph node metastasis." (PMID 36520032, 2023). "Moreover, qRT-PCR results suggested that the GSK3B level was markedly higher in PC tumor tissues as well as PC cell lines." (PMID 36819133, 2023). "Finally, we demonstrated that overexpression of GSK3β dramatically suppressed tumor growth, angiogenesis, EMT, and the expression of β‐catenin and MYH9 in animal models generated by SAMD9 overexpressing ESCC cells." (PMID 36757050, 2023). "Similarly, this study detected significant p-GSK3β elevation but decreased nuclear Nrf2 levels in tumor tissues treated with QRHXF." (PMID 36860928, 2023). "As a tumour promoter or inhibitor, AKT/GSK‐3β plays a key role in tumour development." (PMID 35567291, 2022). "The regulation patterns of GSK3β among tumor types are different or even completely opposite." (PMID 35606353, 2022). "All this data strongly supports the pro-tumour function of GSK-3β." (PMID 36430630, 2022). "SUMOylation of GSK-3β and upregulation of specific SUMO E3 enzyme of GSK-3β in the tumor microenvironment can inhibit the growth of malignant tumor, which may be used as a potential target for cancer treatment." (PMID 35847921, 2022). "Tumor-associated mutations in CTNNB1 exon three target the N-terminal phosphorylation domain of β-catenin protein, resulting in impaired phosphorylation by GSK-3β, increased β-catenin protein stabilization, and nuclear β-catenin protein accumulation." (PMID 35053583, 2022). "Based on this knowledge, we questioned whether ASIC1a‐mediated EMT induces tumour tolerance through the AKT/GSK3β/Snail pathway." (PMID 35426224, 2022). "BDNF-AS recruits EZH2 to down-regulate GSK-3β and silence the tumor-promoting gene GSK-3β." (PMID 35236381, 2022). "GSK3β participates in a variety of signaling pathways to regulate a plethora of cellular activities, such as metabolic activities, transcriptional regulation, neuronal functions, vesicle transport, cell cycles, as well as tumorigenesis and tumor development." (PMID 35265070, 2022). "We further investigated whether inhibition of GSK3β was essential for the tumour‐promoting functions of PPP1R14C in TNBC." (PMID 35090098, 2022). "Furthermore, CAFs-Exo remarkably increased miR-1290, β-catenin, c-Myc and Cyclin D1 level and reduced GSK3β level in tumor tissues; however, these phenomena were all reversed by anti-miR-1290 treatment." (PMID 35999213, 2022).
tumor (continued). "Accordingly, lower phosphorylation levels of p-HER2 (Tyr1248), p-EGFR (Tyr845), p-Akt (Ser473), p-mTORC1 (Ser2448), and p-GSK3β (Ser9) were observed in tumor tissue after combination treatment with 1,25(OH)2D3 and si-LL-37, compared to 1,25(OH)2D3 treatment alone." (PMID 35039485, 2022). "GSK3β upregulates the activity of NF-κB, and the enhanced activity of NF-κB further stimulates and participates in the pathways of cell proliferation, the production of the tumor promoting cytokines and the promotion of anti-apoptosis." (PMID 35265070, 2022). "By binding to its ligand, LOX-1 can activate NOX/MAPKs/NF-κB or PI3K/Akt/GSK3β signaling pathways, regulate the expression of genes such as inflammation, hypoxia, and oxidative stress, and then promote tumor growth, migration, and invasion by effective new blood vessels." (PMID 35449557, 2022). "To verify whether circLIFR exerts tumor-suppressive effects via the circLIFR/miR-624-5p/GSK-3β axis, we performed rescue assays to assess whether GSK-3β could reverse the cellular functions of circLIFR in HCC." (PMID 35581180, 2022). "This synergistic inhibitory treatment catalyses on the varied GSK-3β involvement in multiple signalling pathways to increase DNA damage and impair DNA repair, as well as alter the tumour microenvironment to reduce cell migration, cancer stemness, and metabolic pathways." (PMID 36430630, 2022). "Therefore, activation of GSK‐3β can increase the sensitivity of mPTP opening and inhibit tumour growth via this mechanism." (PMID 35748101, 2022). "In addition, deregulation of GSK-3β expression and activity promotes tumour suppressor activity via JNK, Rb, Notch, TFEB, and C-Myc signalling pathways." (PMID 36430630, 2022). "Previously, NDRG1 has been reported interacting with GSK3b to promote tumor growth." (PMID 35563887, 2022). "In addition to several reported eEF2K-interacting proteins like eEF235 and Homer1,36 GSK3β, a key regulator of tumor immunity by inducing phosphorylation-dependent PD-L1 proteasomal degradation, was shown to be a potential partner of eEF2K." (PMID 35347072, 2022). "Therefore, GSK-3β inhibition has the potential to directly reinforce the immunoreactivity of T- and NK cells infiltrating the tumor microenvironment." (PMID 35681507, 2022). "IHC assay was utilized for the levels of KRAS, β-TrCP, GSK-3β or ANAPC2 in tumor tissues." (PMID 35305671, 2022). "Overall, CLL is a neoplastic disease where GSK-3β seems to play two contrasting roles." (PMID 35681507, 2022). "Increased p‐GSK3β‐Ser9 promotes cell proliferation and tumour growth in TNBC." (PMID 35090098, 2022). "Moreover, ectopic expression of PTEN attenuated tumour cell invasion as well as Akt and GSK-3β phosphorylation and EMT marker proteins enhanced by CDX2 knockdown, while knockdown of PTEN antagonised the tumour-suppressive effect of CDX2 overexpression." (PMID 33239678, 2021). "However, GSK3b is a multifaceted enzyme targeting numerous protein substrates involved in both tumor cell growth and suppression." (PMID 34064422, 2021). "•GSK-3β depletion alone enhances T cell mediated tumor rejection." (PMID 34142056, 2021). "Inhibition of GSK-3β leads to the loss of LAG-3 on T cells and enhanced tumor clearance." (PMID 34356465, 2021). "Furthermore, GSK-3β promotes tumor cell apoptosis by inhibiting HIF-1α and facilitating apoptotic transcription factors." (PMID 33805447, 2021). "Depending on cell type and phosphorylation status, GSK-3β may show tumor suppressor or promoter effect." (PMID 35317111, 2021). "An increase in AKT, GSK-3β, mTOR, 70s 6 kinase was revealed in cancers with point mutation compared with the primary tumor without a mutation." (PMID 34319022, 2021).